CD4 (CD4 molecule)
Diseases named in the same sentence as CD4 in open-access papers (continued):
Sharing a sentence is not in itself a finding about the gene and the disease.
infection (continued). "The viral persistence during the chronic phase of the infection is due in part to latent HIV reservoirs in resting CD4+ T cells and additional cell populations." (PMID 21994747, 2011). "It is possible that this mechanism is responsible for the observation that in progressing HIV-infected subjects, CD4-specific responses to HIV antigens are lost early in infection and are difficult to restore or induce." (PMID 21752277, 2011). "Similar pattern was observed in SIV-infected rhesus macaques, where the variation in the intrinsic ability of their CD4+ T cells to produce TRIM5α had greater effect in late than in early infection." (PMID 21359149, 2011). "In blood, there was a transient yet significant (P<0.0001) increase in percentages and absolute numbers of CD69+CD4+ T cells at 10 days of infection, but this subsequently declined." (PMID 22096538, 2011). "CD4 T cells were shown to be necessary for the development of fully functional CD8 T cells in a variety of infection models." (PMID 21901102, 2011). "One possibility is that NK cells recruit CD4+ T cell to the site of infection, thus supporting the establishment and spread of the infection." (PMID 21408213, 2011). "In this study, we demonstrate a further effect of DC-SIGN that contributes to enhanced infection either in cis or in trans, namely significantly increasing the half-life of the envelope glycoprotein:CD4 complex which in turn promotes co-receptor engagement." (PMID 22163292, 2011). "The endocytosis inhibitors, dynasore and Eps15-DN, suppressed the CD4-independent HIV-1 vector infection, showing that the CD4-independent infection occurs through endosomes." (PMID 21541353, 2011). "Although the antibody response is very important in subsequent protection against infection, CD4+ and CD8+ T-cell responses also play a role." (PMID 22194870, 2011). "There was an increase in the total splenic CD4+ cells in STMΔhfq infected mice compared to the naive as well as the STM-WT infected mice 7 days post infection." (PMID 21347426, 2011). "Considering the central role of CD4+ cells in the immune system, this implies worse immunity for adults born in the hungry/high infection season." (PMID 21676219, 2011). "Prior to infection protectively vaccinated mice exhibit augmented CD4 and CD8 IFNγ and memory responses as well as decreased IL-10 and IL-13 responses." (PMID 21695103, 2011). "It is surprising, however, that the entire population of MZ and FO B cells appears to be engaged in the early response to infection under the coordination of conventional CD4+ T cells." (PMID 21814579, 2011). "Because cathepsin B is activated by low pH in acidic endosomes, we further examined the potential roles of endosomes in the CD4-independent infection." (PMID 21541353, 2011). "The 2-fold increase in the conventional splenic CD4+ T cell population a week after infection results from the vigorous proliferation of these cells, which requires the interaction with DC and class II MHC molecules." (PMID 21814579, 2011). "2W:I-Ab-specific CD4+ T cells then began to decline and reached 10% of the maximum level by day 20-post infection." (PMID 21966268, 2011). "The transfer of purified LCMV-immune CD4+ T cells to CD8-depleted mice largely restored the relative and absolute number of LCMV-specific CD4+ T cells producing IFNγ at day 8 and 11 after infection." (PMID 21966366, 2011). "In TE671 cells, the Eps15-DN rather enhanced the CD4-dependent HIV-1 vector infection provably due to elevated expression of CXCR4." (PMID 21541353, 2011). "Treatment of 293T, TE671, and HeLa cells with these inhibitors attenuated the CD4-independent mNDK vector infection in a dose-dependent manner." (PMID 21541353, 2011).
infection (continued). "IFN-γ produced by Th1 CD4 cells and antigen presenting cells (APCs) augments phagocytic bactericidal activity in patients with infection, and is a useful metric of host immune response to infection, and we considered it as such in the cell culture experiments." (PMID 21711552, 2011). "Compared to cells from the unchallenged mice, airway CD4+ T cells recovered within 24 hours of secondary infection had induced a variety of inflammatory genes consistent with their reactivation to infection." (PMID 21647373, 2011). "Our results demonstrated that both thermally dimorphic forms of P. marneffei activated DCs and promoted DC-mediated HIV-1 trans-infection of CD4+ T cells." (PMID 22110688, 2011). "IRIS is defined as a paradoxical worsening or unmasking of infections, autoimmune diseases or tumours after initiating of cART, and is usually seen when the initial CD4 count is low." (PMID 21955517, 2011). "Infection with M. tuberculosis induces a robust T cell responseinvolving CD4+ and CD8+ T cells and the effectorcytokines IFN-γ and TNF, which are all essential for control of infection, yet adaptiveimmunity fails to eradicate M. tuberculosis." (PMID 21637811, 2011). "SIVsmE660 infection of naive MCM (Group C) led to an overall reduction in circulating CD4+ lymphocyte percentages which were preserved in Group A vaccinates." (PMID 21853072, 2011). "Kinetic studies indicated that deterioration in the ability of effector CD8+ T cells to produce cytotoxic molecules and cytokines begins at 2 weeks post infection (wpi), the same time point when CD4+ Treg expansion is peaking." (PMID 21943070, 2011). "The Ehrlichia Hsp60 and P28-19 peptides are likely to induce CD4+ T cell responses as we detected antigen-specific IFN-γ-producing memory CD4+ T cells in mice infected with E. muris on day 45 post-infection." (PMID 22114733, 2011). "On day 3 post infection, the number of CD4+ T-cells was similar in both groups (control versus infected)." (PMID 21388530, 2011). "The limited studies that have investigated the role of IL-13 in pathogen infection have focused on this molecule as a cytokine that is produced by activated CD4+ Th2 cells." (PMID 21573182, 2011). "The rapidity with which risk increases following HIV seroconversion is striking, rising 2-3-fold within the first 2 years of infection even prior to substantial depletion of the blood CD4 cell count." (PMID 20936108, 2011). "Following intranasal inoculation with GAS-2W, antigen-experienced 2W:I-Ab-specific CD4+ T cells were identified in the nasal-associated lymphoid tissue (NALT) that produced IL-17A or IL-17A and IFN-γ if infection was recurrent." (PMID 21966268, 2011). "The end of acute infection is associated with the emergence of specific CD4+ and CD8+ T cell responses and the establishment of a chronic phase of infection." (PMID 21994747, 2011). "In contrast, CA-074Me treatment attenuated the CD4-independent vector infection in a dose-dependent manner in 293T cells, whose cathepsin B activity was extremely low." (PMID 21541353, 2011). "It is generally accepted that non-conventional CD4+ T cells are particularly shaped for early immune responses to infections while conventional CD4+ T cells are responsible for acquired immunity." (PMID 21814579, 2011). "Of interest, a study that repeatedly immunized macaques with long-standing ART-treated SIVmac251 infection induced stronger SIV-specific CD4+ and CD8+ T cell responses in blood." (PMID 21752277, 2011). "Tregs at the sites of infection are associated with dysfunctional CD8+ T cells and can inhibit both HIV-specific CD4+ and CD8+ T cell responses in vitro." (PMID 21943070, 2011). "It restricts infection of a monocytic cell line and is expressed in primary CD4+ T cells, monocytes and macrophages." (PMID 22082156, 2011).
infection (continued). "The ability of the HIV-1 envelope glycoprotein variants to bind the gp41 HR2 peptide (C34-Ig) in a spontaneous manner was tightly correlated with the ability to mediate CD4-independent infection." (PMID 21731494, 2011). "During infection with murid herpesvirus 4 (MuHV-4), CD4+ T cells antiviral effector function has been demonstrated to be CD8-independent but dependent on IFN-γ secretion." (PMID 21859474, 2011). "This assumption is valid early in infection if we assume the system is well-mixed as there are approximately CD4+ T cells in a human, and perhaps 10-fold less in a macaque, and our model only follows the infection process until 32 cells are infected." (PMID 21304934, 2011). "CD4+ T-cell counts declined rapidly during the first 4 weeks post-infection and decreased progressively thereafter in the 3 groups of animals." (PMID 21850259, 2011). "Despite the differences in the disease course in the three types of untreated infections, prolonged survival in HIV-1, SIVmac and SHIV was found to be linked to better viral control and CD4+ T cell recovery during chronic phase." (PMID 21359149, 2011). "Removal of the V1/V2 loops increased infection of CD4−CCR5+ cells and decreased infection of CD4+CCR5+ cells, similar to the effect of the N197S change." (PMID 21731494, 2011). "Infection with the human immunodeficiency virus 1 type-1 (HIV-1) causes a severe and selective depletion of the CD4+ T lymphocytes both in vivo and in vitro." (PMID 21284907, 2011). "Here, we have examined survival and re-activation of CD4+ T cells in this P. chabaudi infection, and found that more CD4+ cells are activated on re-infection during chronic infection than when infection is eliminated after one month." (PMID 22039531, 2011). "It is accepted that infection with wild-type SIV rapidly induces a depletion of CD4+CCR5+ memory T cells in the GALT." (PMID 21291552, 2011). "Total splenocytes were isolated from the naive mice and mice infected with either STM-WT or STMΔhfq at various time points (4th and 7th day post infection) and stained with anti-CD4+ or anti-CD8+ specific antibodies." (PMID 21347426, 2011). "Approximately1–2% of the transferred P25TCRTh1 cells were stimulated to produceIFN-γ in vivo at that time point, and this percentage was similarto the frequency of total endogenous lung CD4+ T cellsexpressing IFN-γ on day 21 post-infection." (PMID 21637811, 2011). "To measure proliferation and airway accumulation of CD4+ T cells in response to secondary infection, we used two approaches." (PMID 21647373, 2011). "Accumulating evidence support a key role for CD4+ T cells in the acute and chronic stages of the infection in many bacterial diseases." (PMID 21269437, 2011). "Although H3 infected mice normally have few CD4+CD25+FoxP3+ cells, H3 infection of γδ cell deficient mice results in significant increases in Treg cells and suppression of myocarditis." (PMID 21255407, 2011). "First, ART can improve the CD4 cell count profile of a population and therefore decrease progression from infection to TB disease." (PMID 21999773, 2011). "CD25High CD4+ regulatory T cells (Treg cells) have been described as key players in immune regulation, preventing infection-induced immune pathology and limiting collateral tissue damage caused by vigorous anti-parasite immune response." (PMID 21655351, 2011). "Expansion of 2W:I-Ab-specific CD4+ T cells was first detected three days after primary infection with GAS-2W and increased rapidly to a peak seven days after inoculation." (PMID 21966268, 2011). "In this system, the HIV-stimulatory effect of N. gonorrhoeae was less apparent in the co-infected primary CD4+ T cells at the tested multiplicity of infection (MOI) of 10 bacteria per cell, however the effect did still trend towards stimulation." (PMID 21526113, 2011).
infection (continued). "The fact that Tetramer+CD4+ cell numbers per spleen are comparable in I-Ab-/- and WT mice, showing a similar increase following infection, suggests that the antigen presenting cell (APC) function is preserved in the absence of conventional CD4+ T cells." (PMID 21814579, 2011). "As expected, TLR4 signal activation by CD4-TLR4 reduced the CD4-independent vector infection in 293T cells." (PMID 21541353, 2011). "Ten animals per experimental group were chosen based on statistical considerations and on the assumption that the depleted group would show a dramatic increase in disease severity if the CD4+ T cells were involved in control of the infection." (PMID 21663697, 2011). "We found that conventional CD4+ T cells are the main protagonists of the immune response to infection, which develops in two consecutive phases concomitant with acute and chronic parasitaemias." (PMID 21814579, 2011). "This allowed the parallel monitoring of primed endogenous CD4+ and OT-II cells during secondary infection." (PMID 21647373, 2011). "These epitopes induced responses of CD4+ T cells and Th1 (T helper cells) type cytokine responses during the infection." (PMID 21269437, 2011). "In this regard it has been demonstrated that the differences in infectivity between Nef-deleted and wild-type virions are more pronounced upon infection of cells that express lower amounts of CD4." (PMID 22103831, 2011). "It is also of outstanding relevance to consider the influence of pre-erythrocytic stages on the spleen CD4+ T cell response to infection, a limitation of our study that only addresses the immune response to blood-stage parasites." (PMID 21814579, 2011). "This suggests that the threshold level of CD4+ T cells predicting survival corresponds to the minimum level of CD4+ T cells required to preserve immune function in the chronic phase of infection." (PMID 21359149, 2011). "At the portal of infection in the female genital tract, i.e.vaginal, ecto- and endo-cervical tissues, CD4+ T-cells are dispersed within a few focal aggregates." (PMID 21284901, 2011). "A previous study also identified duration of infection as a predictor of CD4+ response, but duration was based upon time from the first recorded HIV test rather than the entire estimated period of HIV infection, as this analysis was able to do." (PMID 21244701, 2011). "During the acute SIVagm infection of RMs, increases in immune activation (HLA-DR) and cell proliferation (Ki-67) were observed for both CD4+ and CD8+ T cells." (PMID 21829366, 2011). "Both P.B3019 (chronic infection) and JVP008 (resolved infection) had detectable DR15-restriced CD4+ T cells with varying avidities for the tetramers." (PMID 21197453, 2011). "We demonstrated that IFN-alpha (IFNα)-induced mature DCs restricted HIV-1 replication and trans-infection of CD4+ T cells." (PMID 21504576, 2011). "Concurrent with the kinetics of the antiviral CD4+ T cell response during acute retroviral infection were the expansion and activation of a subpopulation of natural regulatory T cells at sites of infection." (PMID 21943070, 2011). "Our group showed that CD4+ thymocytes are depleted in large areas of the RAG-hu thymus following infection by CXCR4-tropic virus by immuno-staining." (PMID 21835012, 2011). "Of these 50,358 patients, 34,088 (67.7%) presented with a more advanced form of the infection (more severe clinical and immunological profile), characterized by a CD4+ T cell count ≤100 cells/mm3 or death soon after entry into HIV care." (PMID 21283618, 2011). "Following multiple infections, most of the CD4+CD44Hi2W:I-Ab+ T cells had elevated levels of intracellular IL-17A." (PMID 21966268, 2011). "The endosome acidification inhibitors are thought to enhance the CD4-independent HIV-1 vector infection by suppressing cathepsin B activity, because cathepsin B is activated by low pH in acidic endosomes." (PMID 21541353, 2011).
infection (continued). "The first was to pulse recovered animals with 5′-bromodeoxyuridine (BrdU) and monitor the appearance of divided CD4+ T cells in various organs during secondary infection." (PMID 21647373, 2011). "Cytotoxic CD4+ T cells have been reported after infection with various pathogens and several mechanisms of cytotoxicity have been described." (PMID 21966366, 2011). "We used microarray analysis to assess these changes in flow cytometry sorted subsets of peripheral blood CD4+ T cells from infected rhesus macaques in contrast to their paired pre-infection status." (PMID 22043290, 2011). "Our data suggest that, upon infection, NK and NKT cells are the cell populations involved in early IFN-γ production and that CD8+ and CD4+ T cells are the main IFN-γ producers at later moments of response to infection (7th day)." (PMID 22206036, 2011). "Vaccination with R/D regimen not only induces a heightened multi-functional CD4 Th1 cell response, but also demonstrates a significant control on the bacillary multiplication in the early as well late phase of infection." (PMID 21533158, 2011). "Alternatively, target cells expressing higher levels of CD4 are more prone to productive infection, compared to cells with a lower surface density of the HIV receptor." (PMID 22103831, 2011). "Infection induces transcriptional changes in airway CD4+ T cells, including the up-regulation of a panel of inflammatory chemokines and cytokines, as well as the anti-inflammatory cytokine IL-10." (PMID 21647373, 2011). "DCIR facilitates viral capture and CD4+ T-lymphocyte trans-infection by promoting increased interactions between HIV-1 gp120 and CD4 and/or mediating viral endocytosis into non-degradative endosomes permitting the intracellular storage of intact virions." (PMID 20934454, 2011). "The CD4+ T cells carry out several functions that are important to control infection in the granuloma." (PMID 21234341, 2011). "Together, these results indicate that MDDCs stimulated by PMm and PMy enhanced their capacity to mediate HIV-1 trans infection of CD4+ T cells." (PMID 22110688, 2011). "The gastrointestinal (GI) tract is the major site of HIV replication, which results in massive depletion of lamina propria CD4+ T cells, in the first 3–6 weeks of infection and is maintained throughout the chronic phase." (PMID 21994747, 2011). "The infectivity of the virus secreted in breast milk- and blood- cell culture supernatants was assessed by infection of in vitro activated CD4+ T cells provided by healthy blood donors." (PMID 21569457, 2011). "For instance, in addition to their role in recruiting CD8 CTL to sites of infection via release of Th1 cytokines, CD4 T cells can kill VZV-infected cells." (PMID 22102814, 2011). "Bile salt-stimulated lipase (BSSL) from human milk potently binds DC-SIGN and blocks DC-SIGN mediated trans-infection of CD4+ T-lymphocytes with HIV-1." (PMID 21386960, 2011). "All but 2 subjects had complete lymphocyte count data (29 from each season); while 59 (30 hungry/high infection and 29 harvest/low infection) had full CD4+ and CD8+ counts." (PMID 21676219, 2011). "On the host side, specific immune mechanisms are required to control viral replication in the SG: Depletion of CD4 T cells abolished viral control in the SG with sustained viral replication up to 10 weeks post infection." (PMID 21901102, 2011). "Animal studies have found that CD4+ T, CD8+ T, and CD19+ B cells achieved peak values within 5-6 d after S-OVI infection, whereas the CD4+CD25+ Treg cell count reached its peak at 24-48 h after infection." (PMID 21569236, 2011). "By reducing fbpB expression duringchronic infection, M. tuberculosis restricts the availability ofAg85B, an immunodominant antigen, and thereby prevents infected APCs from optimallyactivating CD4+ effector T cells." (PMID 21637811, 2011).